FOXO1 (forkhead box O1)
Diseases named in the same sentence as FOXO1 in open-access papers (continued):
Sharing a sentence is not in itself a finding about the gene and the disease.
cancer (continued). "Increasing evidence indicates that inhibition of FOXO1 in cancer cells promoted cell cycle transition and cell proliferation by upregulation of cyclin D1." (PMID 36210843, 2022). "The results revealed a lower acetylation level of FOXO1 in cancer tissues than in normal bile duct tissues, demonstrating that CDM-induced autophagy was indeed correlated to FOXO1 acetylation." (PMID 35126526, 2022). "When the patient’s disease progressed to EBII stage, the expression of FOXO1 protein decrease dramatically, suggesting that FOXO1 gene plays an important role in cancer development of MDS." (PMID 36290822, 2022). "Among them, miR‐9, miR‐21, and miR‐222 were previously reported to be involved in the regulation of FoxO1 expression by binding the 3′UTR of FoxO1 mRNA in cancer cells." (PMID 35038382, 2022). "The results of this study are consistent with previous reports demonstrating that FoxO1 inhibited Twist1 mRNA expression in cancer cells." (PMID 33772986, 2022). "Previous studies demonstrated that activation of the PI3K pathway suppressed the expression of FoxO1 in regulating the cell proliferation of several cancer cells." (PMID 35057469, 2022). "Our present data extend this previous work by showing that skeletal muscle expression of FoxP1 is increased in multiple models of cancer cachexia in which FoxO factors are also elevated, and by further identifying FoxP1 as a downstream target of FoxO1." (PMID 33527776, 2021). "Another participant in the complex interplay is 14-3-3 zeta, a regulator of intermediary metabolism recently recognized to promote cancer development by hindering Foxo1 activity." (PMID 33801718, 2021). "In summary, FoxO1 has various functions and regulates the progression of multiple types of cancer through numerous pathways." (PMID 34539243, 2021). "Albeit, FoxO members (in particular FoxO1 and 3) are primarily regarded as inducers of atrophy, their role in cancer progression as well as cancer cachexia still remains to be elucidated." (PMID 33419963, 2021). "As an oncogenic factor, miR-370 functions as a promoter for cancer progression through targeting TGFβ-RII or FOXO1." (PMID 34329193, 2021). "FOXO1 plays an active role in cancer cell migration, invasion, and metastasis in specific cancers or diseases." (PMID 34635635, 2021). "Immunohistochemical staining (IHC) analysis demonstrated the clear upregulation of USP7 and EZH2 accompanied by the downregulation of FOXO1 in these cancer tissues compared to the normal tissues." (PMID 33849069, 2021). "Previous studies have shown that the miR-340, LGR5, and FOXO1 genes have an effective role in the suppression or progression of various types of cancer as well as in the decrease or increase of drug sensitivity against chemotherapy." (PMID 33718760, 2021). "As a forkhead box transcription factor, forkhead box O1 (FOXO1) has been found to participate in cancer development." (PMID 34035814, 2021). "In mammalians, the Foxo subfamily includes four genes of forkhead box-O transcription factors (Foxos), Foxo1, Foxo3, Foxo4, and Foxo6 that play a key role in cancer." (PMID 35178394, 2021). "In normal cell lines, FOXO1 interacted more frequently with regions in active than with regions in inactive subcompartments, but this trend was reversed in cancer cells, supporting a physical repositioning of the FOXO1 locus in the chromatin 3D structure." (PMID 33972523, 2021). "In malignant neoplasms, FoxO1 is an important tumor suppressor gene and is inhibited in many types of tumors during their development." (PMID 34202122, 2021). "The overexpression of AGK can reduce the activation of FOXO1 activity and its downstream targets, thereby enhancing the proliferation and tumorigenicity of cancer cells." (PMID 34368119, 2021). "Since the PI3k/AKT axis is often constitutively activated in cancer and its deactivator PTEN is often mutated or deleted in cancer, preventing it from repressing AKT signaling, FOXO1 is often repressed in cancer." (PMID 34299605, 2021).
cancer (continued). "In metastatic bladder cancer cells, miR-145-5p directly targets FOXO1, hence triggering the anchorage-independent growth of cancer cells in vitro and cancer growth in vivo." (PMID 33435156, 2021). "The FOXO1 locus was in A.1.1 or A.1.2 in all normal cells and it shifted towards intermediate and inactive compartments in cancer cell lines." (PMID 33972523, 2021). "In line with the positive impact of FOXO1 on LDHA, FOXO factors can be associated with cancer-promoting activities and even cause resistance to Temozolomide (TMZ)." (PMID 34831287, 2021). "Although some biologic therapies antagonizing FOXO1 activity were reported in treating cancers, wound repair, and cardiovascular diseases, many efforts are still focused on designing small-molecule compounds indicated for treating metabolic disorders." (PMID 31936903, 2020). "FOXO1 belongs to the forkhead family of transcription factors, which play roles in myogenic growth and differentiation, cancer development, and therapy." (PMID 33262946, 2020). "FOXO1 is a tumor suppressor protein involved in inhibiting the migration and proliferation of cancer cells." (PMID 32503307, 2020). "In support of this, it has been demonstrated that oxidative stress–induced CREB-binding protein (CBP)/p300 acetylates FOXO1 at Lys245, Lys248 and Lys262 to restrict its DNA binding in cancer." (PMID 32372224, 2020). "In a meta-analysis, miR-27a was showed as a new potential FoxO1 regulator during muscle wasting in cancer cachexia; miR-27a inhibits the expression of FoxO1, so as to inhibit muscle atrophy." (PMID 33043011, 2020). "The major types of malignant tumors show FOXO1 inactivation by hyperactivation of PI3K/Akt signaling." (PMID 32948132, 2020). "The ubiquitination and proteasome degradation of the FOXO1 protein are essential in tumorigenesis and represent a viable target for cancer treatment." (PMID 31936903, 2020). "Forkhead box transcription factor O1 (FOXO1) exerts antitumor effects in various cancers, including PCa." (PMID 32047567, 2020). "MicroRNAs, such as miR-107, miR-132, miR-223 and miR-1269, have been shown to negatively regulate FOXO1 expression to promote cell proliferation in a number of cancer cells." (PMID 32372224, 2020). "Due to the limitation of conditions, we do not have a suitable animal model of MDS to further verify activated FOXO1 and their extracellular factors in cancer cells, stromal cells, and immune cells." (PMID 33584800, 2020). "Although the effect of CR in Foxo1-null mice should be investigated, our lifespan studies suggest a differential regulation of cancer and lifespan by CR via Foxo1 and Foxo3." (PMID 31888201, 2019). "Several tissue culture experiments have shown that FOXO1 is down-regulated in a wide variety of cancers, such as breast, kidney, prostate, and uterine cervix cancers." (PMID 31823759, 2019). "We further show that PTEN-mutated cancer cells are resistant to EZH2 inhibitor-mediated killing, but the resistance can be overcome by docetaxel-induced nuclear localization of FOXO1." (PMID 31410199, 2019). "Depletion of FGFR2 in cancer cells attenuated the hypoxia-mediated cell invasion, while forkhead box O1 (FOXO1) expression increased in smooth muscle cells and cardiomyocytes under hypoxia." (PMID 30867905, 2019). "Activated FOXO1 also triggers apoptosis in many cancer cell lines by regulating various proapoptotic proteins, including Fas ligand, TRAIL, and Bim." (PMID 31027497, 2019). "The accumulated FOXO1 promotes transcriptional expression of SOX2, a transcriptional factor for cancer stemness, which in turn, activates FOXO1 transcription and forms a positive regulatory loop." (PMID 31844113, 2019). "Activation of MAPK/ERK signaling pathway has also been reported to impair autophagy by promoting degradation of Fork head Box O1 (FOXO1) in cancer cells." (PMID 31186406, 2019).
cancer (continued). "In fact, Akt is activated in the cachectic muscle of tumor-bearing mice and cancer patients, which inhibits FoxO1/3, resulting in decreased activity of UPP and ALP." (PMID 31480237, 2019). "In cancer cells, dissociation of the FoxO1 transcription factor from SIRT-2 during oxidative stress or starvation results in the acetylation and binding of FoxO1 to Atg7, which subsequently induces autophagy." (PMID 31277291, 2019). "It is well known that CCNB1 triggers mitosis in the G2 phase to promote cell proliferation and tumorigenesis by phosphorylation and inhibition of FOXO1 in cancers after binding to CDK1 and initiating the kinase activity 17-19." (PMID 31592235, 2019). "Both FoxO1 and FoxO3a are sufficient to induce skeletal muscle wasting, and inhibition of FoxO protects against cancer cachexia in mice." (PMID 31769424, 2019). "In early studies using mice with germline-deleted Foxo1, -3, and -4 genes, deletion of a single gene had little effect on longevity or cancer development in postnatal life under AL conditions." (PMID 31888201, 2019). "During CRPC progression, miR-204 targets SIRT1 gene, which is involved in cancer drug resistance by FOXO1 deacetylation." (PMID 31756185, 2019). "While these data support miR-96 targeting of RARγ, other studies have identified additional targets in prostate and other cancers including the pioneer factor FOXO1." (PMID 30120411, 2019). "Consistently, β-catenin levels were upregulated (P < 0.001), but FOXO1 levels were downregulated in HCC compared with those in para-carcinoma tissues (P < 0.001)." (PMID 31695788, 2019). "FOXO1 gene is involved in several biological functions of cancer cells such as cell proliferation, apoptosis, cell differentiation, and angiogenesis." (PMID 30478420, 2018). "It is worth mentioning that ZBTB16 and FOXO1 were also involved in the pathways in cancer according to the KEGG analysis." (PMID 29439675, 2018). "Forkhead box protein O1 (FOXO1) belongs to the forkhead family of transcription factors which are characterized by a distinct forkhead domain and play many important roles in cancers." (PMID 29796115, 2018). "Down-regulation of FOXO1 has been detected in various cancers, and FOXO1 is down-regulated approximately 30-fold in HCC specimens compared with normal liver tissues." (PMID 27924058, 2017). "Recently, it was reported that HDAC inhibitors induce autophagy through FOXO1-dependent pathways in human cancer cells." (PMID 28036259, 2017). "As a result, miR-145-induced IRS1 reduction decreases phosphorylation of AKT and sustains FOXO1 activity to suppress cancer cell growth." (PMID 27999212, 2017). "FOXO1 is also a target of many cancer-related miRNAs, including miR-96, miR-183-96-182 cluster, miR-196a, miR-9, miR-705, miR-137." (PMID 27999212, 2017). "FoxO1 was then found to be regulated by microRNA-21 to control cancer cell proliferation, and FoxO1-low, microRNA-21-high cells had CSC-like properties." (PMID 27705906, 2016). "Skp2, as a part of the SCF-Skp2 E3 ubiquitination complex, is required for the removal of several key proteins as Myc, FOXO1, cancer-derived Smad 4 mutants, ISG15 isopeptidase UBP43, and other proteins." (PMID 26682002, 2016). "Except for the transcriptional activity of FoxO1, cytosolic FoxO1 is able to induce autophagy in human cancer cells upon oxidative stress or serum starvation." (PMID 27010363, 2016). "While direct targeting of the 3’UTR of FOXO1 mRNA by miR-223 has been demonstrated in cancer cell lines, a significant decrease in FOXO1 expression has only been observed in mPE, and not sPE." (PMID 27529341, 2016). "Decreased FOXO1 expression has been shown in many cancer types, such as Hodgkin lymphoma, breast cancer and alveolar rhabdomyosarcoma." (PMID 27835585, 2016).
cancer (continued). "It was reported that SIRT1-mediated FOXO1 deacetylation plays a key role in regulating diverse cellular processes such as differentiation and proliferation in cancer cells." (PMID 26646449, 2016). "MTDH also down-regulated many transcriptional inhibitor factors such as FOXO1 and FOXO3a and thus promoted malignant cancer cell proliferation." (PMID 26287185, 2015). "(2007) reported functional redundancy of Foxo1, Foxo3, and Foxo4 in the regulation of lifespan and cancer in mice under the AL condition." (PMID 25808402, 2015). "FOXO1 activation in OS cell lines inhibited cancer cell survival, which can be attributed to modulation of target genes, including BIM and repressed Wnt/β-catenin signaling." (PMID 26344693, 2015). "The findings in Foxo3+/– mice contrast with those in Foxo1+/– mice reported previously by our laboratory suggest differential regulation of cancer and lifespan by DR via Foxo1 and Foxo3." (PMID 25808402, 2015). "Interaction of FOXO1 (a direct activator of ATGL) and SIRT1 (an activator of FOXO1) led to activation of FOXO1 which is linked with increased tumorigenicity of cancer cells via acylglycerol kinase." (PMID 25569080, 2015). "Collectively, these reports establish a connection between SIRT1 regulation of FOXO1, a transcription factor that in turn can influence cell growth and lipid mobilization in cancer cells." (PMID 25569080, 2015). "The results in Foxo3+/− mice contrast with those in Foxo1+/− mice suggest differential regulation of cancer and lifespan by DR via Foxo1 and Foxo3." (PMID 25808402, 2015). "Our data suggest a negative regulatory loop between mTORC2 signaling and miR-491-3p mediated by FOXO1 in chemo-resistant tong cancer cells." (PMID 25749387, 2015). "In the current study, we find that cytosolic FoxO1 indeed stimulates cellular autophagy in multiple cancer cell lines, and that it regulates not only basal autophagy but also that induced by rapamycin and that in response to nutrient deprivation." (PMID 25546383, 2014). "In contrast to FoxO1, we find the closely related FoxO3a is a negative regulator of autophagy in multiple cancer cell lines, a previously unrecognized function for this protein, different from its function in benign fibroblast and muscle cells." (PMID 25546383, 2014). "Elevated SKP2 (an oncogenic subunit of the Skp1/Cul1/F-box protein ubiquitin complex) levels are found in a wide variety of human cancers, which can recognize the Ser256 phosphorylated FOXO1 and degrade it by polyubiquitination." (PMID 24864265, 2014). "Foxo1 is dysregulated in many cancers and the possibility of its therapeutic manipulation is avidly investigated." (PMID 25330112, 2014). "As it has been shown in other cancer types that miR-96 can regulate FOXO1 levels and FOXO1 has been described to inhibit proliferation this would explain the proliferative phenotype of miR-96." (PMID 23951320, 2013). "FOXO1 expression was able to discriminate between cancer tissue and normal adjacent tissue as assessed by ROC analysis (AUC: 0.70, P >0.001)." (PMID 24260486, 2013). "MiR-27a is located at chromosome 19 and has been shown to function as oncogene by targeting prohibitin, FOXO1 and Sprouty2 in various cancers including GC." (PMID 23613822, 2013). "In this subset FOXO1 was expressed in 22% of all cancer specimens, while in the specimen with high miR-96 expression only 15% also had detectable FOXO1 expression." (PMID 24260486, 2013). "The FOXO1 tumor suppressor is located at 13q41, an area often deleted in PCa and other cancers, and both nuclear FOXO1 and transcript levels have been shown to be decreased in PCa." (PMID 23951320, 2013).
cancer (continued). "In this study, in analogy with the molecular mechanism of RAG expression in B cells, we explored the regulatory mechanism of RAG expression in cancer cells by analyzing the transcription factors E2A, Ikaros, PAX5β, FOXO1, FOXP1 and NF-κB." (PMID 21655267, 2011). "Over-expression of E2A, FOXO1 or Foxp1 increased RAG expression, while RNA interference of E2A, FOXO1 or FOXP1 decreased RAG expression in the cancer cells." (PMID 21655267, 2011). "For example, it was discovered that Skp2 regulates the rate of degradation of the Cdk inhibitor p21 and of the forkhead transcription factor FOXO-1, two other cell cycle regulatory proteins that play important roles in cancer progression." (PMID 16859513, 2006). "Notably, CD47 demonstrated consistently high expression across all four cancer types, whereas forkhead box O1 (FOXO1) exhibited significantly reduced expression in these cancers." (PMID 40396172, 2025). "Thus, FOXO1 overexpression presents a promising approach for improving the effectiveness of T cell-based cancer immunotherapies." (PMID 40093905, 2025). "This would suggest that inactivation of FOXO1 by PRMT1 methylation in cancer cells might attenuate cancer progression." (PMID 40001488, 2025). "Furthermore, FOXO1 is reported to prevent tumorigenesis and is dysregulated in many cancers, such as prostate, breast, and cervical cancer." (PMID 41436994, 2025). "Other antioxidants mediated by FOXO1 may also be involved in the antioxidant defense processes of cancer cells." (PMID 41124013, 2025). "STAT3 may induce genes that suppress cancer progression, such as FOXO1, p14ARF, and CDKN1A (P21), as previously reported." (PMID 41104968, 2025). "Forkhead box O‐1 (FoxO1) acts as an important transcription factor as a regulator of critical cellular processes with implications in aging and diseases, such as metabolic disorders and cancer." (PMID 40679946, 2025). "Furthermore, our analysis, complemented by a pan‐cancer immunotherapy CRISPR screen (five cancer types), pinpointed FOXO1 as a key MR involved in immune resistance." (PMID 38899748, 2024). "Additionally, after assessing the mRNA levels of selected genes, we compared the PIK3CA, PTEN, and FOXO1 protein expression between cancer and normal tissue using images from the Human Protein Atlas." (PMID 38891994, 2024). "Because the activity of FOXO1 is regulated at the post-translational level rather than through changes in transcription and is therefore hidden in RNA-seq data, the role of FOXO1 in cancer immunology and immunotherapy is likely to have been considerably underappreciated." (PMID 38600391, 2024). "MiR-205-5p can also increase cancer cell proliferation and reduce apoptosis by affecting FOXO1." (PMID 38542261, 2024). "Notably, FOXO1 activity in pre-infusion CAR T cells and TILs strongly correlated with clinical responses, underscoring the importance of FOXO1 in T-cell-based cancer immunotherapies." (PMID 38600391, 2024). "Their study proposed that CAP could effectively target cancer stemness by inhibiting the AQP3/FOXO1 axis." (PMID 39438918, 2024). "Cytoplasmic FoxO1‐mediated Atg7‐promoted autophagy has been reported in cancer cells." (PMID 38149787, 2024). "The purpose of this study wasto reveal the roles of FOXO1 in pan-cancer (33 cancers in this study)." (PMID 38716982, 2024). "According to theanalysis of the KEGG pathway, genes associated with FOXO1 could potentially havefunctions in transcription disorder in cancer, whereas FOXO1 itself solely functionsas a regulator of transcription." (PMID 38716982, 2024). "As these mutations are expected to interfere with the phosphorylation of Thr24 by AKT, FOXO1 may be dephosphorylated, activated, and stabilized in cancer cells." (PMID 38519029, 2024). "Many studies have shown that FOXO1 induces autophagy in cardiomyocytes and cancer cells." (PMID 38846640, 2024). "In this research, we examined the expression of FOXO1 in pan-cancer using the TCGAdatabases." (PMID 38716982, 2024).